CLPTM1L (CLPTM1 like)
Diseases named in the same sentence as CLPTM1L in open-access papers (continued):
Sharing a sentence is not in itself a finding about the gene and the disease.
lung adenocarcinoma (14 papers, 2010 to 2025). A carcinoma that arises from the lung and is characterized by the presence of malignant glandular epithelial cells. "Since increased expression of CLPTM1L is associated with lung tumors, we aimed to modulate CLPTM1L levels in the lung adenocarcinoma cell lines and determine the response to genotoxic agents." (PMID 22675468, 2012). "CLPTM1L is often overexpressed in lung adenocarcinoma and its silencing increases cisplatin-induced apoptosis of tumor cells." (PMID 40278994, 2025). "Then, Selamat and TCGA datasets confirmed that CLPTM1L was expressed at higher levels in lung adenocarcinoma than in normal lung tissues and was positively expressed in various NSCLC tissues." (PMID 32943060, 2020). "Here we find CLPTM1L expression to be increased in lung adenocarcinomas compared to matched normal lung tissues and in lung tumor cell lines by mechanisms not exclusive to copy number gain." (PMID 22675468, 2012). "Knockdown of CLPTM1L in A549 and H838 lung adenocarcinoma cell lines was performed using three independent viral shRNA vectors and resulted in a range of efficiencies up to 90% as measured by quantitative real-time PCR and by immunoblot." (PMID 22675468, 2012). "Gene variations rs2736100 and rs2853676 in TERT and rs401681 and rs31489 in CLPTM1L had significant direct associations on lung adenocarcinoma without indirect effects through nicotine dependence." (PMID 25233467, 2014).
ovarian carcinoma (14 papers, 2011 to 2024). A malignant neoplasm originating from the surface ovarian epithelium. "Many types of research have demonstrated that overexpression of CLPTM1L on the plasma membrane of ovarian cancer cells was associated with poor outcomes in serous ovarian adenocarcinoma." (PMID 37497408, 2023). "Kaplan–Meier analysis of the effect of CLPTM1L expression on progression free survival in ovarian cancer patients with TCGA data using KM Plotter18 showed an association of high CLPTM1L expression with poor outcome with a hazard ratio of 1.57 (log rank p = 6.6 × 10−6)." (PMID 33654182, 2021). "Except for the cell-autonomous effects of CLPTM1L on the resistance, they also found CLPTM1L from exosomes conferred chemo-resistance to bystander ovarian cancer cells in an ectodomain-dependent manner." (PMID 37497408, 2023). "Robust re-sensitization of resistant ovarian cancer cells to platinum-based therapy was achieved using human monoclonal biologics inhibiting CLPTM1L in both orthotopic isografts and patient-derived cisplatin resistant xenograft models." (PMID 33654182, 2021). "With survival rates in ovarian carcinoma depending largely on sustained response to platinum based therapies, primarily carboplatin, we sought to determine if CLPTM1L contributes to platinum resistance in a therapeutically targetable manner." (PMID 33654182, 2021). "Another gene in 5p15.33 was CLPTM1L that is expressed in various cancer types, including lung and ovarian cancers." (PMID 27876019, 2016). "CLPTM1L, also known as cisplatin resistance related gene 9 (CRR9), has been found to be overexpressed in human ovarian cancer cells that are resistant to cisplatin-induced apoptosis." (PMID 25415319, 2014). "The role of CLPTM1L was initially described in ovarian cancer cells, where overexpression of the gene induced apoptosis in cisplatin-sensitive cells." (PMID 25007268, 2014). "Palate transmembrane 1-like (CLPTM1L), also called cisplatin resistance related gene 9 (CRR9), was identified among the genes involved in resistance to the anticancer drug cisplatin in ovarian cancer cells." (PMID 23300716, 2012). "Cleft lip and palate transmembrane 1-like (CLPTM1L), also called cisplatin resistance-related gene 9 (CRR9), is a 62 kDa protein of 538 amino acids that was identified among the genes involved in resistance to the anticancer drug cisplatin in ovarian cancer cells." (PMID 32943060, 2020). "CLPTM1L is upregulated in a cisplatin-resistant ovary cancer cell line and might be involved in the apoptotic response of cells under genotoxic stress caused by cisplatin." (PMID 26621837, 2016). "For example, CLPTM1L, as a predicted transmembrane protein, is upregulated in cisplatin-resistant ovarian cancer cell lines, and may be involved in the apoptotic response of cells to cisplatin-induced genotoxic stress." (PMID 25007268, 2014). "However, for a long time, the functions of CLPTM1L gene were poorly understood, and it was observed as a cisplatin-resistance factor in ovarian cancer-cell lines which can't be taken as a function of CLPTM1L gene on oncogenesis." (PMID 24194831, 2013). "Therefore, human anti-CLPTM1L mAbs could re-sensitize to platinum-resistant ovarian cancer cells achieved in orthotopic isografts and patient-derived cisplatin-resistant xenografts models." (PMID 37497408, 2023).
melanoma (11 papers, 2013 to 2025). A malignant, usually aggressive tumor composed of atypical, neoplastic melanocytes. "The TERT/CLPTM1L region is frequently identified by GWAS for conferring tumor risk for many tumor types, including pancreatic, lung, melanoma, and bladder cancers (see refs 16, 17 for meta-analyses)." (PMID 28781888, 2017). "The CLPTM1L gene encodes a membrane protein whose overexpression in cisplatin-sensitive cells causes apoptosis, and polymorphisms at this locus have been reported to increase susceptibility to many cancer types, including melanoma." (PMID 39199954, 2024). "Genes in cluster 8 (GSTO2, LRRC34), 9 (CLPTM1L) and 10 (CTSS, SETDB1, ANXA9, GOLPH3L, HORMAD1, PPIL3, CASP9, ALS2CR12) underlie the association between melanoma and cancers." (PMID 38308491, 2024). "Among these, one region on chromosome 5p15.33 harboring the TERT and CLPTM1L genes had statistically significant shared heritability for seven cancer types, including ER-negative breast, colorectal, glioma, lung, melanoma, pancreatic, and prostate cancer." (PMID 34355204, 2021). "To determine the effect of ZNF148 depletion on expression of TERT and CLPTM1L in pancreatic, lung, testicular, and melanoma cell lines (n=8 total), we used siRNA-mediated PTGS." (PMID 28447668, 2017). "The results also included 10 SNPs previously identified for melanoma risk reported at MC1R (2 SNPs), MX2, TERT/CLPTM1L, PLA2G6, CASP8, ACTRT3, ASIP, CDC91L1, and ARNT/SETDB1/LASS2ANXA9/MCL1/CTSK." (PMID 27993549, 2017). "One region on chromosome 5 (982,252–2,132,442 bp), harboring the TERT and CLPTM1L genes, showed significant local genetic correlation across six pairs of cancers, including ER-negative breast, colorectal, glioma, lung, melanoma, pancreatic, and prostate cancer." (PMID 34355204, 2021). "Interestingly, in the 57,490,258–58,411,259 pb region of chromosome 21 associated with two traits (VM and VN), we found five candidate genes (LPCAT1, CLPTM1L, TERT, TRIP13, and BRD9), all of which were related to the main types of skin cancer, i.e., melanoma and cutaneous squamous cell carcinoma." (PMID 39199954, 2024).
cervical cancer (9 papers, 2010 to 2025). A primary or metastatic malignant neoplasm involving the cervix. "Overexpression of CLPTM1L has also been associated with poor prognosis of oral cancer patients and cervical cancer recurrence." (PMID 40278994, 2025). "We identified novel variants in PAX8 and CLPTM1L intronic regions in UK Biobank samples, which were replicated in the FinnGen dataset of cervical cancer phenotypes." (PMID 33794208, 2021). "Lead SNP rs27069 in the CLPTM1L gene was also replicated in invasive cervical cancer (p=2·54 × 10−7), CIN3 (p=0·04), and cervical dysplasia (p=0·0004) phenotypes." (PMID 33794208, 2021). "Our results provide new evidence for the genetic susceptibility to cervical cancer, specifically the PAX8, CLPTM1L, and HLA genes, suggesting disruption in apoptotic and immune function pathways." (PMID 33794208, 2021). "In a recent study on cervical cancer integrating gene dosage and expression data, the CLPTM1L/TERT locus was found to have copy number gain in tumors and expression patterns that correlated with copy number gain." (PMID 22675468, 2012). "Another recent study revealed that with copy number gain across 5p, CLPTM1L expression was increased approximately 5 fold in cervical cancer cell lines over normal cervical epithelial cells, while expression of the other genes at 5p15.33 was not changed." (PMID 22675468, 2012). "In the cervical cancer study, CLPTM1L emerged from the 5p locus as having expression patterns that correlated with copy number gain." (PMID 22675468, 2012). "For example, we identified eRNA‐QTL in CLPTM1L eRNA (CLPTM1Le) exhibited strong colocalization with cervical cancer risk loci (PPH4 = 0.92) in uterus tissue, but not with eQTL (PPH4 = 0.01)." (PMID 39950845, 2025). "A recent GWAS has confirmed the importance of HLA genes for the genetic susceptibility to cervical cancer, along with new risk variants in the PAX8 and CLPTM1L genes, suggesting a disruption in apoptotic and immune function pathways plays a key role in the susceptibility to HPV-associated cancers." (PMID 34683414, 2021). "Here, we review cervical cancer susceptibility variants arising from recent genome-wide association studies and meta-analysis in large cohorts and propose 2q14 (PAX8), 17q12 (GSDMB), and 5p15.33 (CLPTM1L) as consistently replicated non-HLA cervical cancer susceptibility loci." (PMID 34680286, 2021). "Three SNPs were replicated in the independent Finnish dataset of 1648 invasive cervical cancer cases: PAX8 (rs10175462; p=0·015), CLPTM1L (rs27069; p=2·54 × 10−7), and HLA-DQA1 (rs9272050; p=7·90 × 10−8)." (PMID 33794208, 2021). "Three of these SNPs, PAX8 (rs10175462), CLPTM1L (rs27069) and HLA-DQA1 (rs9272050) were replicated in the independent Finnish dataset of 1648 invasive cervical cancer cases." (PMID 34683414, 2021).
bladder cancer (6 papers, 2013 to 2025). "We confirmed the presence of VNTR polymorphism in CLPTM1L using genomic DNA obtained from cancer-free controls and bladder cancer patients." (PMID 38254939, 2023). "We confirmed that all MS regions followed Mendelian inheritance, and demonstrated that MS2 alleles increased CLPTM1L promoter activity in the UM-UC3 bladder cancer cells through a luciferase assay." (PMID 38254939, 2023). "The findings of this study suggest that the CLPTM1L VNTR region may be associated with bladder cancer risk through the modulation of CLPTM1L gene expression." (PMID 38254939, 2023). "Thus, we recommend further research to validate the link between CLPTM1L genetic variants and the progression and responsiveness to anticancer drugs by analyzing clinical data from bladder cancer patients." (PMID 38254939, 2023). "Secondly, considering that smoking is a strong risk factor for developing lung and bladder cancer, it is possible that the risk variants identified at the 5p15 locus affect the CLPTM1L gene, thereby influencing the metabolism of carcinogens, and hence modify cancer risk." (PMID 23752272, 2013). "Moreover, genes such as NAT2, TP63, GSTM1, MYC, TACC3‐FGFR3, PSCA, CLPTM1L‐TERT, APOBEC3A‐CBX6, UGT1A, and CCNE1 get mutated in bladder cancer." (PMID 40755497, 2025). "This study represents the first comprehensive characterization of the CLPTM1L VNTR regions, and based on our findings, it may serve as an index for assessing the risk of bladder cancer." (PMID 38254939, 2023). "Notably, our study focuses on the relationship between CLPTM1L variants and the risk of developing bladder cancer, but is limited by the lack of analysis using clinical data from bladder cancer patients." (PMID 38254939, 2023).
glioma (6 papers, 2011 to 2025). A benign or malignant brain and spinal cord tumor that arises from glial cells (astrocytes, oligodendrocytes, ependymal cells). "Mutations in CLPTM1L have been identified as risk factors in a range of cancers, including lung, pancreatic, colorectal, glioma and testicular germ cell cancer, and the expression of CLPTM1L is significantly increased in cancerous cells when compared to healthy adjacent tissues." (PMID 30042348, 2018). "Five of the genes, TERT, SLC6A18, CLPTM1L, and CDKN2A/B, have previously been shown to be associated with glioma by other GWA studies." (PMID 21827660, 2011).
ovarian tumor (6 papers, 2012 to 2025). "Investigating multiple tumor types, we found that CLPTM1L was present in the extracellular vesicle fractions culture media from Panc1 pancreatic and cisplatin resistant variants of ovarian tumor cells." (PMID 33654182, 2021). "The CLPTM1L gene encodes the CLPTM1-like protein which is highly expressed in cisplatin-resistant ovarian tumor cell lines and is associated with cisplatin-induced apoptosis." (PMID 29254260, 2017). "Although a connection of CLPTM1L to cancer is suggested by copy number gain, genome wide association and studies in ovarian tumor cell lines; the function of CLPTM1L and its role in tumorigenesis is thus far unknown." (PMID 22675468, 2012). "It is noteworthy that researchers have recently developed human IgG1 anti-CLPTM1L monoclonal antibodies to resensitize ovarian tumor cells to platinum-based drugs." (PMID 39346724, 2024). "In the present study, we demonstrate that CLPTM1L accumulation is upregulated in platinum resistant derivatives of human ovarian tumor cells." (PMID 33654182, 2021). "In the present study, CLPTM1L protein was found to be more abundant in platinum pre-treated ovarian tumor cells, and anti-CLPTM1L treatment was synergistic with carboplatin killing." (PMID 33654182, 2021). "CLPTM1L was identified as an up-regulated transcript in a cisplatin resistant ovarian tumor cell line." (PMID 22675468, 2012). "CLPTM1L has been identified as an overexpressed protein in human ovarian tumor cell lines that are resistant to cisplatin, which is the only insight thus far into the function of CLPTM1L." (PMID 22675468, 2012). "CLPTM1L, named for its homology with Cleft Lip and Palate Transmembrane Protein 1 that disrupted in a family with cleft lip and palate, was identified as an up-regulated transcript in a cisplatin resistant ovarian tumor cell line." (PMID 23653681, 2013). "This suggests that while endogenous CLPTM1L may mediate chemoresistance through Akt phosphorylation in ovarian tumor cells including A2780, HeyA8, OVCAR5, PeO4, Akt phosphorylation may be a less prominent CLPTM1L-mediated chemoresistance mechanism when it is delivered from extracellular sources." (PMID 33654182, 2021). "However, interpretation of the results of this study is difficult, as there is no implication of mechanism and the effect of overexpression of CLPTM1L in cisplatin sensitivity was conflicting in different ovarian tumor cell lines, depending on their pre-existing level of resistance." (PMID 22675468, 2012). "CLPTM1L, also known as cisplatin resistance-related protein-9 (CRR9), was initially identified due to its elevated expression in cisplatin-resistant ovarian tumor cell lines." (PMID 40550808, 2025). "We show that CLPTM1L is broadly overexpressed and accumulated on the plasma membrane of ovarian tumor cells, while weakly or not expressed in normal tissues." (PMID 33654182, 2021).
breast carcinoma (5 papers, 2017 to 2025). "The most highly mutated DHS in breast cancers is at chr5:1325957-1328153, located within an intron of CLPTM1L and 30 kb upstream of TERT." (PMID 28874753, 2017). "Additionally, previous studies have shown that transcription factor CTCF binds to CLPTM1L promoter and regulates its expression in breast cancer cell." (PMID 40550808, 2025).
non-small cell lung carcinoma (4 papers, 2013 to 2020). A group of at least three distinct histological types of lung cancer, including non-small cell squamous cell carcinoma, adenocarcinoma, and large cell carcinoma. "Rs465498 in the CLPTM1L gene has been reported to be associated with non-small cell lung cancer (NSCLC)." (PMID 23658731, 2013).
cleft lip (3 papers, 2013 to 2024). Congenital defect in the upper lip where the maxillary prominence fails to merge with the merged medial nasal prominences. "The chromosome 5p15.33 locus contains two well-known genes, telomerase reverse transcriptase (TERT) and cleft lip and palate trans-membrane 1-like (CLPTM1L), which have been implicated in carcinogenesis." (PMID 24260099, 2013). "Cleft lip and cleft palate transmembrane protein 1 (CLPTM1L, alias CRR9) was responsible for encoding cleft lip and palate-associated transmembrane 1-like proteins." (PMID 39255319, 2024).
endometrial cancer (2 papers, 2015 to 2024). Primary or metastatic malignant neoplasm involving the endometrium (mucous membrane that lines the endometrial cavity). "To identify possible mechanistic associations between TERT, CLPTM1L and endometrial cancer, we searched for information on endometrial gene expression and somatic variation in publically available datasets." (PMID 25487306, 2015). "Using TCGA RNASeq data we found significantly increased expression of both TERT and CLPTM1L in endometrial cancer tissue compared with normal tissue (TERTP = 1.5 × 10−18, CLPTM1LP = 1.5 × 10−19)." (PMID 25487306, 2015). "Additionally, there is genetic overlap between UL and endometrial cancer, with implicated genes including CLPTM1-like (CLPTM1L), microRNA 4457 (MIR4457), TERT, WT1 transcription factor (WT1), and WT1 antisense RNA (WT1-AS)." (PMID 38790186, 2024). "Several studies have reported associations between multiple cancer types and single-nucleotide polymorphisms (SNPs) on chromosome 5p15, which harbours TERT and CLPTM1L, but no such association has been reported with endometrial cancer." (PMID 25487306, 2015).
lymph node metastasis (2 papers, 2012 to 2021). "In conclusion, the present study demonstrated that the expression of two ER stress-related proteins, Clptm1L and TMEM207 immunoreactivity was closely related to lymph node metastasis with prognostic value in patients with OSCC." (PMID 35047994, 2021). "Coexpression of Clptm1L and TMEM207 was closely related to lymph node metastasis (P=0.000574)." (PMID 35047994, 2021).
myeloma (2 papers, 2018 to 2019). "Our results suggest that the CLPTM1L gene has a higher RPKM value in myeloma cells than in healthy donor cells." (PMID 30079703, 2019). "The expression of PLPP5, CLPTM1L and ITM2C varied between different established human myeloma cell lines, however, all cell lines examined had detectable expression of at least one of these genes of interest." (PMID 30042348, 2018).
oral cancer (2 papers, 2017 to 2025). "In the UK Biobank database, CLPTM1L was significantly associated with various cancer phenotypes, including lung, upper digestive tract, pancreatic, testicular, nasopharyngeal, and oral cancer." (PMID 40278994, 2025). "The rationale of choosing these CNA associated genes was basically due to LRP12, TPM2, EGFR, CCND1 being matched with ICGC and TCGA databases whereas FSCN1, CLPTM1L, CHL1 and CSMD1 had been found to be associated with oral cancer." (PMID 28384287, 2017).
oral squamous cell carcinoma (2 papers, 2021 to 2024). "Encoding a transmembrane protein, CLPTM1L exhibits heightened expression across various malignant tissues, including the lung lung, ovary, pancreas and Oral Squamous Cell Carcinoma." (PMID 39346724, 2024). "In the present study, we examined whether these two ER stress-related proteins, Clptm1L and TMEM207, could be prognostic markers in oral squamous cell carcinoma (OSCC)." (PMID 35047994, 2021).
skin cancer (2 papers, 2022 to 2024). "Interestingly, rs401681 could affect transcription regulation, result in the over-expression of the CLPTM1L gene, and increase risk of lung and skin carcinoma." (PMID 35847915, 2022).
cervical tumours (1 paper, 2021). "CLPTM1L codes for a transmembrane protein and has been linked to cell growth promotion in non-cervical tumours, and altering cisplatin-mediated apoptosis when overexpressed." (PMID 33794208, 2021).